RET (ret proto-oncogene)
Diseases named in the same sentence as RET in open-access papers (continued):
Sharing a sentence is not in itself a finding about the gene and the disease.
tumor (continued). "According to ASCO guidelines, patients with EC should undergo comprehensive biomarker assessments, including HER2, PD‐L1, dMMR/MSI‐H, NTRK, BRAF, RET, and tumor mutational burden (TMB) testing." (PMID 39415846, 2024). "Tumour tissue DNA sequencing revealed a heterozygous somatic pathogenic variant p.(Met918Thr) in exon 16 of the RET gene." (PMID 38804700, 2024). "In RET fusion-positive PTCs, features associated with higher tumor aggressiveness were detected more often than in PTCs positive for other mutations." (PMID 37882481, 2023). "Future studies should elucidate tumor cell-autonomous effects versus effects of a RET-deficient ENS." (PMID 39148929, 2023). "In a study that sequenced 39 different histological types and a total of 4,871 tumor tissue samples, only 1.8% of solid tumors had RET gene variants, of which the gene fusion types accounted for 30.7%." (PMID 37927605, 2023). "For advanced MTC patients with unresectable tumor recurrence or distant metastasis, patients with RET mutation or fusion will likely receive RET inhibitor therapy and other measures." (PMID 37519823, 2023). "A phase I/II clinical trial (NCT04161391) aims to investigate TPX-0046 efficacy, safety, and tolerability in drug-resistant and naïve RET-altered tumor models with Solvent Front Mutations (SMF)." (PMID 37568193, 2023). "In the treatment choice physician should consider a variety of clinical factors like the tumor volume, the precise location, symptoms, the clinically significant structural disease progression, and the RET mutational status." (PMID 37979019, 2023). "LOXO-260 is an investigational anti-tumor drug targeting RET fusions and mutations, designed following the success of LOXO-292 (selpercatinib)." (PMID 38201460, 2023). "RET mutation can cause tumor cell survival and proliferation, induce c‐cell transformation, finally exerting their oncogenic effects on the thyroid." (PMID 37081757, 2023). "They analyzed 75 patients with confirmed sporadic MTC diagnosis, a serum calcitonin measurement > 100 pg/mL, and a tumor tissue harboring the RET p.M918T mutation (50/75)." (PMID 37568824, 2023). "Distribution of RET mutation-positive cases in this cohort as per their demographic, tumor stage, MEN component, and mutation (n = 15)." (PMID 38260132, 2023). "A small percentage of NSCLC cases have specific changes in the RET gene that cause abnormal production of the RET protein, leading to increased tumor cell growth." (PMID 37901797, 2023). "The prevalence of somatic RET M918T mutation frequency increases with tumour size, from 11.3% in microMTCs to 58.8% in MTCs larger than 30 mm." (PMID 37835559, 2023). "Dysfunctional RET signaling was associated with gene expression changes in diverse tumor signaling pathways in tumors and normal-appearing colon." (PMID 39148929, 2023). "Certain RET fusion proteins and activating point mutations can drive oncogenesis and tumor progression by activating downstream signaling pathways, leading to uncontrolled cell proliferation." (PMID 36900367, 2023). "RET fusion-positive carcinomas were associated with aggressive tumor behavior, including high rates of lymph node (75.2%) and distant metastases (18.6%), significantly higher than in NTRK fusion, BRAF V600E and RAS-positive carcinomas." (PMID 37882481, 2023). "In cases of apparently sporadic MTC, the identification of a RET germline mutation is of marked clinical utility because it facilitates the identification of subjects who will develop the tumour." (PMID 37207147, 2023). "A rat model of cardiac cachexia shows a protective effect of a neutralizing monoclonal anti-GDF-15 antibody, and an antagonistic monoclonal anti-GFRAL antibody prevents RET activation and subsequent weight loss in tumor-bearing mice." (PMID 36361969, 2022).
tumor (continued). "Genomic DNA sequencing revealed 2 pairs of bilateral tumors harboring the same BRAF V600E mutation, while the remaining pair of bilateral PTC had different genetic mutations, with BRAF V600E mutation in the right tumor and RET/FARP1 fusion in the left tumor." (PMID 35515000, 2022). "Despite the high histological grade and the coexistence of aggressive RET co-mutations, an impressive metabolic and structural tumor response has been obtained, together with a patient's prolonged clinical benefit." (PMID 36578928, 2022). "Genes found mutated in relapse of patient 1, such as LMO3 or RET, are associated with unfavourable outcome of the disease and tumor progression." (PMID 36037157, 2022). "A prophylactic bilateral lateral lymph node dissection in sporadic tumours should be performed at a basalCT > 600 pg/mL; in the case of RET-mutated tumours this value would be 200 pg/mL." (PMID 35089388, 2022). "Medullary thyroid carcinoma (MTC) is a malignant tumor originating in the parafollicular C-cells of the thyroid resulting from pathologic RET variants, marked by drastic increases in calcitonin levels." (PMID 35685436, 2022). "BLU-667 has been shown to induce tumor regression in cancer models with RET mutations and fusions, dasatinib has been shown to reduce NB growth as early as 2009, and spebrutinib has antitumor activity in large B-cell lymphoma." (PMID 36147739, 2022). "RET-selective TKIs offer patients harboring RET-variant related disease a much needed option for systemic therapy, providing both substantial tumor responses and a tolerable toxicity profile." (PMID 35685436, 2022). "We here found RET oncogene variants in 44/48 prospectively collected MTC tumor samples from patients treated with more unselective kinase inhibitors vandetanib and/or cabozantinib." (PMID 35884466, 2022). "For basalCT values < 200 pg/mL in sporadic tumours and 87 pg/mL in tumours with the RET mutation, the probability of finding affected lymph nodes in the central compartment was < 10%." (PMID 35089388, 2022). "In our study’s subgroup analysis, we identified different basalCT values between sporadic tumours and tumours associated with the RET mutation." (PMID 35089388, 2022). "PTC, both in adults and children, is the neoplasm with the highest prevalence of RET fusions (5–30%), especially when associated to ionizing radiations." (PMID 34373541, 2021). "The pathogenesis of this tumor is related to activating RET mutations that are germline in hereditary cases (approximately 98% of cases) and somatic in sporadic cases (approximately 45% of cases)." (PMID 34680178, 2021). "We gained some insight into its function by comparing transcriptome abundances between BAP1 mutation/deletion and BAP1 wild type tumours, where we found replicated up-regulation of the RET proto-oncogene." (PMID 34580349, 2021). "For examples, for cabozantinib the presence of M918T somatic RET mutation in tumor sample seems to be associated with better overall survival, while on the contrary for vandetanib a drug resistance was associated with V804M RET mutation." (PMID 33803747, 2021). "We recently demonstrated that the prevalence of RET somatic mutations is higher in MTC of a larger tumor size, suggesting that the presence of this genetic alteration can induce a higher cell proliferation rate." (PMID 34680178, 2021). "The correlation between RET somatic mutation and a worse outcome is strengthened by the evidence that the prevalence of RET somatic mutations is higher in patients with a more advanced tumor and lower in patients with smaller tumors." (PMID 33572167, 2021). "The presence of somatic RET mutations has been found to be correlated with a worse prognosis of the tumor and shorter survival." (PMID 33572167, 2021).
tumor (continued). "with RET rearrangements (10–20%), many other neoplasms are associated with RET-fusion involved in creating resistances and escaping mechanisms to classical therapies." (PMID 33806299, 2021). "Some, including miR-224, miR127 and miR-129-5p, are downregulated in RET mutated MTCs due to their tumor suppressor role and/or their preferential activation of the RAS-related pathway." (PMID 33924120, 2021). "We did not observe significant correlations between the presence of RET mutations and primary tumor location and RAS or BRAF status, on the other hand." (PMID 34741450, 2021). "Next‐generation sequencing was performed to detect RET mutations and calculate tumor mutation burden (TMB)." (PMID 34741450, 2021). "Particularly, M918T has been associated with poor prognosis and tumor metastasis in patients with somatic RET mutations." (PMID 34207842, 2021). "A phase I-II trial is investigating the role of TPX-0046, a new potent RET inhibitor, that has shown activity even in tumour models with Solvent Front Mutations." (PMID 34503226, 2021). "Low (H-score < 100) SDHB staining characteristic for SDH-associated tumors was confirmed in all SDHB-associated tumor tissues while a high (H-score ≥ 100) staining was observed in RET-mutant tumors." (PMID 32150977, 2020). "Encouraging results have also been obtained by targeting rare genetic mutations like TRK- and RET fusions in tumour agnostic clinical trials." (PMID 32932925, 2020). "The presence of somatic RET mutations was associated with lymph node and distant metastasis, tumor recurrence, and patient mortality." (PMID 33112827, 2020). "Recently, two molecules especially designed as strong and selective inhibitors, BLU-667 and LOXO 292, have shown promising activity in RET-positive NSCLCs, as well as in other tumours with RET mutations or rearrangements." (PMID 31598903, 2020). "A subgroup analysis showed that the treatment in vandetanib was most beneficial in a subgroup of patients with RET M918T mutation in tumor cells." (PMID 33112827, 2020). "In sample CPN81, a RET mutation (p.C609Y) was found at an allele frequency (AF) of 0.98, indicating a loss of heterozygosity of the wild type allele in the tumor tissue." (PMID 32511227, 2020). "RET fusions were also associated with poor differentiation, solid subtype, presence of signet ring cells, small tumor size, early lymph node metastases, low levels of PD-L1 expression, and poor response to immunotherapy." (PMID 32326537, 2020). "Next, we investigated the oncogenic role of RET mutations in the growth of tumor xenografts in nude mice and found that WT and EV barely increased the growth of A2780 cells." (PMID 32293499, 2020). "A patient with PCC who had a RET mutation (SNP-001) had a total reduction in tumour volume of 64% as best response and remains on treatment after 64 cycles (7 years)." (PMID 31105270, 2019). "In sporadic MTC, the presence of a somatic RET mutation, particularly M918T, has been found to correlate with more aggressive tumor features, a more advanced stage at diagnosis and a worse prognosis." (PMID 31510104, 2019). "The RET gene was mutated in 1 tumor (1.1%), showing two novel mutations in the protein tyrosine kinase domain." (PMID 31548566, 2019). "Somatic RET mutations have been described in sporadic cases of MTC as well as loss of heterozygosity at different loci (deletions of tumor suppressor genes) in MTC." (PMID 31717449, 2019). "The prognosis reported is extremely variable, differing from long term survival and rapid tumor progression in case of poorly differentiated diagnosis, high Ki67 expression and RET mutation." (PMID 31142313, 2019). "A previous study revealed that genetic alternations such as TERT mutations, BRAF V600E mutations, and RET/PTC rearrangement all contributed to the tumor proliferation and metastasis." (PMID 31583243, 2019).
tumor (continued). "At the tumor level, somatic RET mutations, commonly point mutations but also deletions/insertions, have been described in about 50% of the sporadic MTC, according to data published in the COSMIC database." (PMID 31510104, 2019). "Its expression decreased in poorly differentiated mouse tumors, paralleling the loss of RET/PTC3 expression along with tumor progression, thus supporting a role for IL-24 as a tumor suppressor factor." (PMID 31412566, 2019). "The ability of TLG, imaging-based TF, and clinical parameters (including age, tumor marker doubling times, prior therapies and RET (rearranged during transfection) mutational status) for prediction of both PFS and OS were evaluated." (PMID 30206772, 2019). "We believe that if we can offer earlier RET screening for at-risk patients, we will be able to diagnose neoplasms at an earlier stage, or, more desirably, before they have developed." (PMID 30624503, 2018). "Whole-exome sequencing analysis revealed four mutations specific to the resistant tumor, including the RET-S904F mutation." (PMID 29434222, 2018). "This study demonstrated that in about 20% of cases a different RET mutation profile can be found when comparing primary tumor and its corresponding metastases." (PMID 29515777, 2018). "RET mutations fall into two distinct classes based on mutational mechanisms and are consistently associated with distinct tumor types." (PMID 30666215, 2018). "Conversely mutations were somatically acquired and were apparently selected for within the bulk of tumor cells since they represented 20–49% of RET alleles, respectively." (PMID 29665843, 2018). "Recently, a resistance mutation (RET p.Ser904Phe) was identified in a CCDC6-RET fusion tumor in a patient that developed secondary resistance to vandetanib suggesting that similar type of resistance mechanisms as for other targeted drugs can occur." (PMID 29890761, 2018). "RET mutations influence the tumor microenvironment and angiogenesis, and among sporadic cases p.M918T RET has been linked to poor prognosis, compared to MTCs that are RAS mutated or without mutations." (PMID 30140036, 2018). "The resistant tumor acquired a secondary mutation resulting in a serine-to-phenylalanine substitution at codon 904 in the activation loop of the RET kinase domain." (PMID 29434222, 2018). "In particular, we demonstrated that somatic RET mutation prevalence increases with increasing tumor size, reaching a prevalence of approximately 90% in advanced cases." (PMID 29515777, 2018). "The other, a 53-year-old man with a tumor located in the left lobe of the thyroid gland (7 mm in diameter, pT1a), carried polymorphic variants p.Gly691Ser/p.Ser904Ser of the RET gene." (PMID 28647780, 2017). "Cluster 2 contains tumours with mutations in RET, TMEM127, MAX, NF1 and HRAS and is characterized by aberrant activation of kinase signalling pathways." (PMID 28327598, 2017). "Further, the difference in the tumour transcriptome between RET mutations initiating the MEN2A and MEN2B types of MTC is restricted to a few genes, which are related to cell proliferation, growth and differentiation." (PMID 28181547, 2017). "We found that miR-182 expression is significantly upregulated in MTC patient samples and tumor-derived cell lines harboring mutated RET." (PMID 28122586, 2017). "MTC is associated with activators of the RET proto-oncogene, which codes for a membrane receptor of the tyrosine-kinase type of 150-170 kD highly expressed in normal and tumor cells derived from the neural crest, including parafollicular thyroid cells." (PMID 28658345, 2017). "Patients with tumours with high RET nuclear and cytoplasmic expression were at the highest risk of progressive disease and death." (PMID 27092013, 2016). "Tenascin C correlated significantly with tumor proliferation (overall, r = 0.61, p < 0.005; RET-mutated, r = 0.81, p < 0.01)." (PMID 27409604, 2016).
tumor (continued). "Gene mutations in the genes encoding EGFR, FGFR2, KDR, and RET were discovered in the patient's tumor tissue by whole exome sequencing and the patient was treated with a combination of the targeted drugs cetuximab and sunitinib." (PMID 27149458, 2016). "Results showed that the exposure of MTC cells to the NDI derivative resulted in a marked impairment of in vitro tumor cell growth, which was tightly associated with a remarkable down-regulation of RET, both at mRNA and protein levels." (PMID 27351133, 2016). "A reduced overall survival was strongly associated with metastasis in patients with high RET nuclear expression tumours." (PMID 27092013, 2016). "Tenascin C expression correlates significantly with tumor proliferation, especially in RET-mutated tumors." (PMID 27409604, 2016). "Increased RET activity stimulates cell proliferation and transformation by promoting tumor-associated inflammation and recruiting primary immune cells to the tumor microenvironment." (PMID 26294325, 2015). "In multifocal PTCs, previous studies provided evidence that BRAF mutational status or subtypes of RET/PTC differed among tumor foci 7–10." (PMID 25882744, 2015). "For example, CXCR4 expression in tumor cells has been described to be attendant with oncogenic events such as hypoxia, RET/PTC mutations, EGFR variant-mediated invasion, and HER2 overexpression." (PMID 23484027, 2013). "In the present work, a comparative genomic hybridization (CGH) study was performed using DNA from a primary tumor in a M918T RET mutation-positive SMTC patient and from its lymph node metastasis to investigate additional genetic alterations." (PMID 22676344, 2012). "Molecular diagnostic testing confirmed the presence of the M918T RET mutation in the tumor and lymph node metastases previously." (PMID 22676344, 2012). "Oncogenic RET has been implicated in mediating tumor-associated inflammation, as mutant forms of RET induced the expression of IL-8 and other inflammatory molecules." (PMID 23056499, 2012). "Recently Rossi reported three cases of MTC/PTC collision tumour in which two mutations, in the RET and BRAF genes, were identified, thus documenting the different genetic origin of these two coexisting carcinomas." (PMID 17997826, 2007). "A G691S RET polymorphism was present with a higher frequency in radiation-induced epithelial thyroid tumours (55%) than in sporadic tumours (20%) and in control normal thyroid tissues (15%)." (PMID 12085189, 2002). "All the radiation-associated tumours presenting a G691S RET SNP, with the exception of samples Ti 233 and 255, were positive for a RET/PTC1 or RET/PTC3 rearrangement." (PMID 12085189, 2002). "This 691 RET sequence variant was also detected in 20% of sporadic tumours (6/29) and 15% of the control normal thyroid tissues (3/20)." (PMID 12085189, 2002). "We looked then for the eventual presence of RET genetic alterations in our radiation-associated and sporadic tumours as well as in samples of unrelated normal thyroid tissue." (PMID 12085189, 2002). "RET was found to be the dominant mutation of the primary tumour from LNM to DM." (PMID 40729029, 2025). "Additionally, earlier studies primarily focused on the common SNVs (e.g., BRAFV600E) or FAs (e.g., RET), overlooking other critical tumor-suppressor gene mutations." (PMID 40895628, 2025). "Moreover, our finding that KEAP1 mutations not only drive tumor growth and migration but also attenuate cellular response to selpercatinib in RET fusion-positive cells highlights their clinical significance." (PMID 41573641, 2025). "In addition, kinase activation caused by RET fusion promotes cytokine production, contributing to specific biological phenotypes and facilitating tumor initiation and progression." (PMID 40895628, 2025).